TSGA10 (testis specific 10)
Diseases named in the same sentence as TSGA10 in open-access papers (continued):
Sharing a sentence is not in itself a finding about the gene and the disease.
cancer (16 papers, 2009 to 2025). A tumor composed of atypical neoplastic, often pleomorphic cells that invade other tissues. "Ectopic TSGA10 is detected in a multitude of cancers and has been proposed as a diagnostic biomarker for select malignancies." (PMID 35892887, 2022). "TSGA10 is initially characterized as a testis-specific protein and tumor-associated antigen that facilitates angiogenesis and metastasis in various cancers." (PMID 31772141, 2019). "It should be noted however, that TSGA10IP (TSGA10 interacting protein) interacts with TSGA10, a protein also associated with cancer and that binds cytoskeletal proteins (e. g., vimentin and actin-γ1)." (PMID 26569114, 2015). "For instance, DNA hypomethylation at the TSGA10 promoter has been linked to its overexpression in cancers like transitional cell carcinoma, while hypermethylation in other contexts may suppress its expression, contributing to tissue-specific regulation." (PMID 40507237, 2025). "Tissue-specific TSGA10 expression further modulates cancer susceptibility: high levels in the testes and brain may protect against thermal and oxidative damage, whereas low expression in the liver permits HIF-1α-driven metabolic plasticity." (PMID 40507237, 2025). "The tissue specificity of TSGA10’s function—critical in brain and testes but dispensable in liver—mirrors cancer vulnerabilities, where loss of TSGA10 in thermoregulatory tissues could permit heat-induced microenvironmental remodeling (e.g., angiogenesis and immune evasion)." (PMID 40507237, 2025). "While the evidence supporting TSGA10’s role in thermoregulation and cancer is compelling, several questions remain." (PMID 40507237, 2025). "TSGA10, a multifunctional protein critical for mitochondrial coupling and metabolic regulation, plays a paradoxical role in cancer progression and carcinogenesis." (PMID 40507237, 2025). "As previously reported, TSGA10 expression exhibits two distinct phases—downregulation and upregulation—during cancer progression." (PMID 40507237, 2025). "Because of the roles of TSGA10 in spermatogenesis and cancers any changes in this protein can be related to different kinds of conditions." (PMID 39744514, 2025). "TSGA10 exhibits context-dependent roles in metabolic regulation across postmitotic cells and cancer, with its expression levels aligning with distinct cellular energy demands." (PMID 40507237, 2025). "Our model predicts that in cancer, TSGA10 acts as a double-edged sword: Low levels allow ROS buildup and force cancer cells to rely on less efficient energy methods (like glycolysis), promoting tumor growth." (PMID 40507237, 2025). "Meanwhile, TSGA10’s dual role in mitochondrial coupling and metabolic reprogramming positions it as a pivotal regulator in cancer biology." (PMID 40507237, 2025). "Conversely, TSGA10 overexpression in certain cancers suppresses HIF-1α, inhibiting glycolysis and metastasis." (PMID 40507237, 2025). "TSGA10 expression levels reflect a cell’s metabolic priorities—sustaining OXPHOS in postmitotic cells versus restraining glycolysis in cancer—making it a critical node in cellular energy homeostasis." (PMID 40507237, 2025). "So, the expression of TSGA10 is a common feature of both cancer cells and testis tissue cells which have high levels of proliferation in the hypoxia condition." (PMID 39744514, 2025). "Conversely, high TSGA10 levels can suppress tumors by maintaining mitochondrial health and blocking cancer-friendly pathways." (PMID 40507237, 2025). "Ultimately, TSGA10’s ability to enforce metabolic priorities—OXPHOS in healthy cells versus glycolysis in cancer—highlights its potential as a therapeutic target to disrupt tumor metabolic plasticity and restore mitochondrial fidelity in malignancies." (PMID 40507237, 2025). "The various tumor-suppressive effects of TSGA10 on cancer biology can provide a potential opportunity to enhance the efficacy of different cancer therapies." (PMID 39272902, 2024).
cancer (continued). "This review outlines that TSGA10 expression level in cancer cells depends on the cancer stage across malignant transformation." (PMID 39272902, 2024). "Jahani’s and Amoorahim’s studies demonstrate that TSGA10 overexpression can inhibit cancer cell metastasis by reducing its migratory ability and disrupting angiogenesis." (PMID 39272902, 2024). "The next section discusses the role of TSGA10 in cancer progression based on the current understanding of malignant transformation." (PMID 39272902, 2024). "This conceptual review was, therefore, conducted to re-evaluate the available literature regarding the TSGA10 in cancer progression by considering malignant transformation and cancer hallmarks." (PMID 39272902, 2024). "The available TSGA10 literature poses a big question, “Why do cancer cells need to express a protein that prevents their progression?”." (PMID 39272902, 2024). "These interactions suggest that TSGA10 plays a significant role in cancer progression through exosome regulation, although further research is needed to fully understand its mechanisms." (PMID 39272902, 2024). "This review demonstrated that TSGA10 expression level in cancer cells depends on the cancer stage across malignant transformation." (PMID 39272902, 2024). "To answer this question, we reviewed the TSGA10 literature from the scope of “cancer hallmarks” and “malignant transformation”." (PMID 39272902, 2024). "They will analyze both published and unpublished studies and data to understand how TSGA10 functions at different stages of cancer." (PMID 39272902, 2024). "More recent studies revealed that TSGA10 can suppress tumor progression by blocking cancer cell metabolism, angiogenesis, and metastasis." (PMID 39272902, 2024). "This duality has sparked curiosity among researchers worldwide to explore the role of TSGA10 in cancer progression." (PMID 39272902, 2024). "Scientists are particularly interested in TSGA10 because it is found in both normal reproductive tissues and cancer cells, yet seems to slow down cancer progression." (PMID 39272902, 2024). "Given this information, TSGA10 can be of great interest in developing effective targeted anti-cancer therapies." (PMID 39272902, 2024). "The specific expression of TSGA10 in cancer cells can provide an opportunity to limit the anti-mitochondrial effects on cancer cells." (PMID 39272902, 2024). "An open question regarding the TSGA10 is why cancer cells must express a protein that prevents their progression." (PMID 39272902, 2024). "Among these, TSGA10 (testis-specific gene antigen 10) is considered due to its unique impacts on cancer phenotypes." (PMID 39272902, 2024). "Among these, TSGA10 (testis-specific gene antigen 10) is of great interest because of its crucial impact on cancer progression." (PMID 39272902, 2024). "An open question regarding the TSGA10 is why cancer cells need to express a protein that prevents their progression." (PMID 39272902, 2024). "Testis-specific gene antigen 10 (TSGA10) is one of the potential CT-antigens (Cancer/Testis Antigen 79), predominantly expressed in testis and overexpressed in some tumors, such as BTs." (PMID 36860313, 2023). "For example, testis-specific gene antigen 10 (TSGA10) suppresses cancer development in various types of malignant tumours by inhibiting HIF-1 expression, tumour cell metastatic capability, and metabolic activity in breast cancer." (PMID 35574342, 2022). "TSGA10 expression is significantly reduced in cancer patients and the downregulation of TSGA10 is associated with high VEGF levels, tumour angiogenesis and cancer metastasis." (PMID 35574342, 2022). "For both patients and cell lines, cancer testis genes of TSGA10, TEX101 and ODF3 were determined by RT-PCR." (PMID 23396665, 2012).
cancer (continued). "Other antigens so far identified for cutaneous lymphoma include cTAGE and TSGA10 both of which were originally classified as cancer-testis antigens as well as a number of nuclear proteins, proteins of the transcription machinery, metabolic enzymes and others." (PMID 20020065, 2009). "Here, TSGA10’s loss could act as a metabolic “key”, destabilizing OXPHOS fidelity to favor glycolysis, a hallmark of cancer metabolism." (PMID 40507237, 2025). "TSGA10 protein was consider as a kind of cancer testis antigens previously." (PMID 39744514, 2025). "Targeting the hypothesized TSGA10-mediated mitochondrial coupling may offer therapeutic potential to disrupt cancer’s adaptive energetics and restore metabolic homeostasis." (PMID 40507237, 2025). "Also, in cancer cells, we predict that higher TSGA10 expression suppresses glycolysis (via HIF-1α inhibition), aligning with reduced tumor aggressiveness." (PMID 40507237, 2025). "Conversely, therapeutic targeting of the TSGA10-CytC1 axis might restore apoptosis and autophagy/mitophagy in cancer, and energy balance in mitochondrial disorders." (PMID 40507237, 2025). "TSGA10’s varying levels in tissues—high in the brain and testes (protecting against damage) and low in the liver (enabling cancer growth)—make it a promising target for therapies aimed at disrupting cancer’s energy strategies." (PMID 40507237, 2025). "In the testis, TSGA10’s constitutive expression is likely maintained by androgen-responsive elements, whereas in cancers, oxidative stress and metabolic changes may alter its epigenetic or miRNA-mediated regulation." (PMID 40507237, 2025). "TSGA10’s role at the intersection of mitochondrial regulation and environmental adaptation highlights its potential as a therapeutic target for neurodegenerative diseases and cancer." (PMID 40507237, 2025). "TSGA10’s dual association with Complex III (via CytC1) and Complex IV-linked HIF-1α pathways positions it as a critical orchestrator of mitochondrial fidelity, with profound implications for cancer." (PMID 40507237, 2025). "With this information, one may conclude that TSGA10 upregulation can contribute to the cancer cells to retrieve their polarity." (PMID 39272902, 2024). "It has been demonstrated that HIF-1 has inhibitory effects on TSGA10 in cancer cells." (PMID 39272902, 2024). "Further experimental studies are needed to explore the role of TSGA10 in cancer progression." (PMID 39272902, 2024). "Early studies explored TSGA10 expression in a variety of cancer types." (PMID 39272902, 2024). "This study also indicated the negative correlation between TSGA10 and cancer-associated fibroblast (CAF) infiltration." (PMID 39272902, 2024). "As alluded to above, TSGA10 induction can lead to G2/M arrest in cancer cells." (PMID 39272902, 2024). "By uncovering these mechanisms, this research could lead to new targeted therapies that use TSGA10 to combat cancer more effectively, offering fresh insights and potential breakthroughs in cancer treatment." (PMID 39272902, 2024). "In other words, we assume that TSGA10 is a “basic tool” for the early progression of cancer." (PMID 39272902, 2024). "This research aims to explore the role of the TSGA10 protein in cancer development, specifically in how it might influence the growth and spread of cancer cells." (PMID 39272902, 2024). "However, in the following, cancer cells need to downregulate TSGA10 to respond to their progression." (PMID 39272902, 2024). "MiR-10b-3p and miR-23a reduce the expression of TSGA10, thus promoting cancer progression." (PMID 35574342, 2022). "In cancer, TSGA10 has been shown to inhibit angiogenesis by sequestering HIF1-α." (PMID 35892887, 2022). "Thus, this bidirectional repression mechanism not only underscores how tumors hijack metabolic–thermogenic crosstalk to survive stress but also highlights TSGA10 as a potential therapeutic target to restore mitochondrial fidelity and disrupt cancer’s adaptive energetics." (PMID 40507237, 2025).
cancer (continued). "Given TSGA10’s hypothesized role in promoting mitochondrial coupling, its downregulation in cancer may facilitate a shift toward glycolysis, favoring the Warburg effect, where cancer cells preferentially use glycolysis over OXPHOS, even in the presence of oxygen." (PMID 40507237, 2025). "In addition, we evaluated how TSGA10 expression can prevent the “cancer hallmarks”." (PMID 39272902, 2024). "Therefore, upregulation of TSGA10 might prevent the cancer cells from being promoted to the less differentiated phenotypes." (PMID 39272902, 2024). "TSGA10 might target the mitochondrial metabolism and trafficking in cancer cells." (PMID 39272902, 2024). "TSGA10 and Hypoxia-inducible factor 1-alpha (HIF-1α—a protein that helps cancer cells thrive in low oxygen) regulate each other, creating a balance that shapes tumor behavior." (PMID 40507237, 2025). "The mutual counter-regulation between TSGA10 and HIF-1α, which integrates thermoregulation with metabolic reprogramming, has profound implications for cancer." (PMID 40507237, 2025). "Because of normal function of testicular cells without any cancerous status, it is probable that factors such as TSGA10 protein inhibit the HIF function and consequently cancer development." (PMID 39744514, 2025). "Thus, TSGA10 emerges as a potential metabolic gatekeeper whose dysregulation could link mitochondrial coupling defects, ROS-driven mutagenesis, and metabolic reprogramming in cancer progression, offering novel therapeutic targets to disrupt tumor energetics." (PMID 40507237, 2025). "In addition, TSGA10 induction could reduce the cancer cells’ metabolism and metastatic ability." (PMID 39272902, 2024). "The duality in TSGA10 expression and metabolic activity in postmitotic versus cancer cells highlights TSGA10 as a potential metabolic “switch” that reinforces the native metabolic state of the cell—OXPHOS in postmitotic cells and glycolysis suppression in cancer." (PMID 40507237, 2025). "This study analyzed the 5′UTR region of TSGA10 and GGNBP2, considering the significance of the regulatory effects of 5′UTR and unclear mechanisms regulating the expression of TSGA10 and GGNBP2 in normal and cancer cells." (PMID 36860313, 2023). "For instance, TSGA10 (testis specific Gene Antigen 10), which acts as a tumor suppressor in many types of human cancers and inhibits VEGF-induced angiogenesis was not differentially expressed in anti-VEGF resistant condition." (PMID 33803224, 2021). "Moreover, TSGA10’s proposed role in optimizing mitochondrial electron transfer and coupling through Complex III may hold significant implications for cancer biology." (PMID 40507237, 2025). "In addition, engaging TSGA10 induction as a therapeutic approach assumes it can be safely upregulated in cancer cells without adverse effects, which requires investigation." (PMID 39272902, 2024). "Therefore, we screened TF, proto-oncogenes, tumor suppressor genes, and other TAG from the genes adjacent to aberrant DNA methylation sites, of which multiple known cancer related genes, including MYC, DDR1, MEF2C, NDRG2, SIX1, TNFRSF10B and TSGA10, had HyperM phenomena." (PMID 26046465, 2015).
tumor (14 papers, 2012 to 2025). "The over-expression of TSGA10 was associated with tumor suppression and cancerous cell apoptosis." (PMID 36860313, 2023). "Their study demonstrated that TSGA10 expression negatively correlated with the tumor-infiltrating lymphocytes and MHC molecules." (PMID 39272902, 2024). "Our present results confirms that hypoxia-induced HIF-1α activation leads to upregulation of miR-10b-3p, which in turn facilitates tumor growth and metastasis by targeting TSGA10." (PMID 31772141, 2019). "In ESCC, TSGA10 down-regulation is shown to be associated with a progressive clinical stage, and in vivo assays suggest TSGA10 knockdown significantly accelerates tumor growth and leads to larger tumor volumes." (PMID 31772141, 2019). "We believe that exosomes serve as a paracrine mechanism for miR-23a transported from NPC cells to ECs, thereby accelerating angiogenesis in the adjacent tumor endothelium by directly targeting TSGA10." (PMID 29520105, 2018). "Significantly, in this study, we found that reduced expression of TSGA10 enhanced the migration of ECs, suggesting negatively regulating tumor angiogenesis to miR-23a." (PMID 29520105, 2018). "Conversely, in hypoxic or nutrient-deprived microenvironments, residual TSGA10 activity might paradoxically support tumor survival by balancing ROS and ATP production, explaining its context-dependent roles as both an oncogene and tumor suppressor." (PMID 40507237, 2025). "The thermal component of TSGA10’s function—reducing heat from electron leakage—could also influence the tumor microenvironment, where excess heat may promote angiogenesis or immune evasion." (PMID 40507237, 2025). "This positions TSGA10 as a potential key mediator of either oncogenesis or tumor suppression, and may help explain the fact that it has been reported to have both properties." (PMID 40507237, 2025). "Therefore, a decrease in TSGA10 expression in advanced phases of malignant transformation can contribute to developing tumor-promoting inflammation." (PMID 39272902, 2024). "Therefore, TSGA10 overexpression in tumor endothelial cells can enhance the tumor oxygen pressure that inherently improves radiosensitivity." (PMID 39272902, 2024). "The findings suggest that the TSGA10 and GGNBP2 transcript variants might present a functional role, altering the expression patterns of these genes, thereby increasing tumor growth and stimulating malignancy traits." (PMID 36860313, 2023). "Importantly, compelling evidence indicates that testis-specific gene antigen (TSGA10) inhibits tumor angiogenesis and metastasis." (PMID 29520105, 2018). "Given the inhibitory effects of TSGA10 on the HIF-1 axis, TSGA10 overexpression can provide an opportunity to enhance the anti-tumor immune response and, thereby, response to immunotherapies." (PMID 39272902, 2024). "In the GSE15824 dataset, the TSGA10 expression was reduced in the GBM tumor with a log2 fold change of -2.59 and increased in the oligodendrocytoma tumor with a log2 fold change of 2.521." (PMID 36860313, 2023). "Regarding the transcript expression patterns, the relative mRNA expression of TSGA10 and GGNBP2 genes in the BT samples differed from normal testicular tissue; accordingly, the transcripts have a shorter 5′UTR sequence in tumor samples." (PMID 36860313, 2023). "Taken together, our results demonstrate that hypoxia can increase expression of miR-10b-3p, which in turn targets TSGA10, leading to the promotion of ESCC tumor growth and metastasis." (PMID 31772141, 2019). "In summary, some studies introduced TSGA10 as a CGA, while others found it a tumor suppressor." (PMID 39272902, 2024). "Moreover, the interaction between TSGA10 and HIF-1α can prevent the transcriptional activity of HIF-1α and thus interfere with tumor growth, and angiogenesis." (PMID 31772141, 2019).
TSGA10 also shares sentences with these, for which no sentence is quoted: acute lymphoblastic leukemia (2 papers); asthenozoospermia (1); cancer testis (1); cervical cancer (1); female sterility (1); hepatic cancer (1); ovarian serous carcinoma (1); transitional cell carcinoma of the bladder (1).